PTTG1 (PTTG1 regulator of sister chromatid separation, securin)
Diseases named in the same sentence as PTTG1 in open-access papers (continued):
Sharing a sentence is not in itself a finding about the gene and the disease.
lung carcinoma (27 papers, 2006 to 2025). "Dependent on the histological subtype of lung cancer, PTTG-1 expression was associated with a better outcome in patients with SCLC and a rather unfavourable outcome for patients with NSCLCs." (PMID 16426442, 2006). "The 23 kDa PTTG-1 protein consists of 202 amino acids and is located on chromosome 5q33, a locus previously associated with progression of lung cancer." (PMID 16426442, 2006). "This is examplified at its best by our results showing an association between PTTG-1 expression and overall survival of tumor patients in dependence of lung cancer subtype." (PMID 16426442, 2006). "In vitro investigations with lung cancer cell lines revealed that silencing PTTG1 inhibited cell proliferation and invasion." (PMID 38200058, 2024). "We performed PTTG1 immunohistochemical staining of lung cancer tissues and peripheral lung tissues of 17 samples from the Guilin lung cancer cohort." (PMID 39144144, 2024). "Pttg1 is involved in cell cycle regulation and the development of lung cancer, suggesting its role in the lungs." (PMID 39153120, 2024). "In their cohort, they also reported upregulation of PTTG1 was related to poor prognosis of patients with lung carcinoma." (PMID 35251171, 2022). "ADCK5 phosphorylates Sox9 and thereby regulates PTTG1 in lung cancer cells, which leads to a change in the migrative and invasive behavior of these cells." (PMID 35205819, 2022). "Previous studies show that PTTG1 promotes cell migration and proliferation and suppresses cell apoptosis in lung cancer." (PMID 31391849, 2019). "Recently, Maik and Kakar demonstrated that PTTG1 is directly involved in the invasion of lung cancer cells by inducing EMT (epithelial-mesenchymal transition) via integrin-focal adhesion kinase signaling and alteration of MMPs." (PMID 26900962, 2016). "Investigated in tumors, PTTG-1 has been found over expressed in pituitary tumors, thyroid cancer, esophageal squamous cancer, uterine leioma, lung cancer, lymphoid cancer, colon cancer, gastric carcinoma testicular cancer, breast cancer, astrocytoma cancer." (PMID 18384692, 2008). "Further, PTTG-1 overexpression in the human lung cancer cell line A549 inhibited the cell growth via activation of p21." (PMID 16426442, 2006). "Further experiments are needed to understand the different pathways of PTTG-1 in different lung cancer subtypes." (PMID 16426442, 2006). "In the present study, we examined the prognostic value of PTTG-1 expression for survival in relationship to the different histological subtypes of lung cancer." (PMID 16426442, 2006). "In this study, we examined the role of PTTG-1 expression in lung cancer with regard to histological subtype, the correlation of PTTG-1 to clinical parameters and relation on patients' survival." (PMID 16426442, 2006). "PTTG1 was found to promote lung cancer migration and invasion, and knockdown of PTTG1 could enhance anti-tumor activity in LUAD." (PMID 36726580, 2023). "In lung cancer has been demonstrated the concomitant overexpression of PTTG1 or MMP9." (PMID 31572301, 2019). "Since PTTG1 is involved in the invasion of lung cancer cells, we investigated whether PTTG1 induced the invasion ability of HTR-8/SVneo cells using Transwell chamber assays." (PMID 26900962, 2016). "Lung cancers belong to the group of tumors expressing PTTG-1." (PMID 16426442, 2006). "At first glance our results seem to be contradictory but might be a reflection of the varying role of PTTG-1 in the pathophysiology of the different histological subtypes of lung cancer." (PMID 16426442, 2006). "In this study a high prevalence of PTTG-1 expression in lung cancer was seen." (PMID 16426442, 2006).
lung carcinoma (continued). "Moreover, PTTG1 could promote the proliferation and metastasis potential of several human tumor types, such as colon cancer, esophageal cancer, and lung cancer, which suggests the pro-tumor role of PTTG1." (PMID 35768832, 2022). "It regulates the expression of the oncogene human pituitary tumor transforming gene-1 (PTTG1) by phosphorylating the transcription factor SOX9, which enhances the migration and invasion of lung cancer cells." (PMID 37835536, 2023). "Our results provide proof of principle that the CTAs SP17/AKAP4/PTTG1 are expressed in both human NSCLC cell lines and primary tumors and can elicit an immunogenic response in lung cancer patients." (PMID 25739119, 2015). "Some of the predicted master regulators, including PTTG1, RFC4, TRIP13, BUB1B, TTK, and ZWINT are capable of promoting migration, invasion, and metastasis of lung cancer cells." (PMID 36304306, 2022). "As expected, IHC staining revealed that protein expressions of FOXM1, HJURP, and PTTG1 were all significantly elevated in tumors compared with adjacent normal tissues, indicating that SRS genes may play an important in lung cancer progression." (PMID 34869385, 2021).
glioma (25 papers, 2007 to 2025). A benign or malignant brain and spinal cord tumor that arises from glial cells (astrocytes, oligodendrocytes, ependymal cells). "This study suggests the potential roles of a novel hypoxia‐associated CDC20+KIF20A+PTTG1+ cell subpopulation in glioma progression." (PMID 40047299, 2025). "Various research has shown that PTTG1 is linked to tumor formation and prognosis in numerous tumors, such as glioma, KIRC, and LIHC." (PMID 35281830, 2022). "The result showed that the protein encoded by PTTG1 was higher expressed in glioma than normal tissues (#Antibody CAB008373)." (PMID 36527013, 2022). "We identified a unique CDC20+KIF20A+PTTG1+ high‐risk glioma cell subpopulation probably necessary for glioma progression of LGG/GBM transformation, which was further explored in multiple cohorts and validated in samples by immunohistochemistry and multiplex immunofluorescence assays." (PMID 40047299, 2025). "Hence, these results hint that CDC20+KIF20A+PTTG1+ high‐risk glioma cell subpopulation was specifically associated with hypoxia, which may drive this cell subpopulation predominantly via regulating its No.1 marker gene CDC20." (PMID 40047299, 2025). "CDC20, KIF20A and PTTG1 remained co‐expressed in glioma cells, and this cell subpopulation was increased in four recurrence glioma cases under therapy." (PMID 40047299, 2025). "CDC20+KIF20A+PTTG1+ glioma cell subpopulation remains relative higher hypoxia level than other glioma cells in each time point, and increased during long‐term gliomagenesis." (PMID 40047299, 2025). "In conclusion, these findings suggest that the CDC20+KIF20A+PTTG1+ cell subpopulation is critical to glioma progression." (PMID 40047299, 2025). "PTTG1 has been reported to inhibit cell angiogenesis in glioma cells and regulate the G1/S cell cycle process." (PMID 38465336, 2024). "Consistent with the previous results, the protein level of PTTG1 was significantly increased in glioma in comparison to peritumor tissue, while the level of MYC was decreased in tumor." (PMID 36527013, 2022). "Our study also showed the higher expression of PTTG1 in glioma and inhibition of PTTG1 decreased the proliferation and invasion of glioma cells." (PMID 36527013, 2022). "Our studies indicated cell senescence-associated genes such as PTTG1 and MYC influenced the activities of glioma cell obviously." (PMID 36527013, 2022). "Immune infiltration analysis showed that PTTG1 was positively correlated with ImmuneScore, StromalScore, and ESTIMATEScore in tumors such as glioma and kidney tumors." (PMID 35281830, 2022). "To explore the effect of PTTG1 and MYC on glioma cell survival and invasion, we transfected cells with siRNA to downregulate PTTG1 and MYC." (PMID 36527013, 2022). "KEGG pathway analysis showed that PTTG1 was linked to cell cycle, oocyte meiosis, human immunodeficiency virus 1 (HIV-1) infection, glioma, and mismatch repair." (PMID 35281830, 2022). "Enhanced pituitary tumor‐transforming gene‐1 (PTTG1) expression correlates with the unsatisfactory prognosis in patients with glioma." (PMID 34739189, 2022). "For instance, PTTG1 expression was distinctly increased in glioma, and its knockdown suppressed cell angiogenesis and metastasis in glioma cells." (PMID 35251171, 2022). "Patients with high expression of PTTG1 were associated with poor overall survival (OS) in ACC, KIRC, KIRP, lower grade glioma (LGG), LIHC, LUAD, mesothelioma (MESO), PAAD, THCA, and uveal melanoma (UVM) (all p < 0.05)." (PMID 35281830, 2022). "PTTG1 was positively correlated with all the ImmuneScore, StromalScore, and ESTIMATEScore in glioma (GBM + LGG) and pan-kidney cohorts (KICH + KIRC + KIRP) (all p < 0.05)." (PMID 35281830, 2022). "Previously, miR-520d-5p was found to inhibit cell proliferation and cell cycle via targeting PTTG1 in glioma." (PMID 34353336, 2021).
glioma (continued). "Given its anti-tumor effect, miR-520d-5p suppresses human glioma cell proliferation through targeting PTTG1 and inhibits tumor metastasis and growth by binding to CTHRC1 in colorectal cancer." (PMID 32950972, 2020). "Up-regulation of PTTG1 has been correlated with aggressive disease and poor prognosis in hepatocellular carcinoma, prostate cancer, esophageal cancer, glioma, thyroid cancer and colorectal cancer." (PMID 26264222, 2015). "CDC20, KIF20A and PTTG1 were specifically co‐expressed in Bio‐C8 LGG glioma cells." (PMID 40047299, 2025). "Hence, these results suggest that CDC20+KIF20A+PTTG1+ glioma cell subpopulation is potential target in effective TMZ‐sensitizing therapies." (PMID 40047299, 2025). "Then, a series of phenotypic assays were performed to investigate whether CDC20, KIF20A and PTTG1 knockdown inhibits proliferation phenotypes in glioma cell lines." (PMID 40047299, 2025). "Therefore, the CDC20+KIF20A+PTTG1+ cell subpopulation featured aberrant oncogenic molecular activity in glioma, suggesting that these cells are therapeutically vulnerable to glioma progression." (PMID 40047299, 2025). "Moreover, canonical oncogenic proliferation markers MKI67 and TOP2A were upregulated in the CDC20+KIF20A+PTTG1+ cell subpopulation of glioma samples." (PMID 40047299, 2025). "Moreover, spatial atlas of GBM also showed that relative higher hypoxia level in spots of CDC20+KIF20A+PTTG1+ glioma cell subpopulation." (PMID 40047299, 2025). "PTTG1 regulates the G1/S cell cycle process and inhibits cell angiogenesis in glioma cells." (PMID 38465336, 2024). "MiR-520d-5p by targeting PTTG1 could inhibit human glioma cell proliferation and induce G0/G1 arrest." (PMID 33330110, 2020). "The ECT2/PSMD14/PTTG1 axis promoted glioma proliferation by stabilizing E2F1." (PMID 33381564, 2020). "We next tested the expression of PTTG1 in serum EVs from glioma patients." (PMID 31410219, 2019). "We also show the potential of NLGN3 and PTTG1 in EVs for detecting glioma." (PMID 31410219, 2019). "We also demonstrate the efficacy of NLGN3 and PTTG1 mRNA in serum EVs to diagnose glioma patients." (PMID 31410219, 2019). "We also showed the potential of NLGN3 and PTTG1 mRNA in EVs for detecting glioma patients." (PMID 31410219, 2019). "We found negligible mRNA levels of PTTG1 in EVs from healthy donors (n =9) and increased PTTG1 mRNA in EVs from glioma patients (n =18) (nonparametric test, **P <0.01), although the mRNA level of PTTG1 varied in glioma patients." (PMID 31410219, 2019). "However, studies on the expression of PTTG1 in EVs from glioma patients have rarely been reported." (PMID 31410219, 2019). "This subgroup is naturally present at high grades and shows more CDC20+KIF20A+PTTG1+ cells than LGG, suggesting a critical role in glioma progression." (PMID 40047299, 2025). "In order to investigate the influence of PTTG1 and MYC on the invasion of glioma cells, we conducted a 3D collagen spheroid invasion assay." (PMID 36527013, 2022). "IHC staining was performed to detect the representative PTTG1 and MYC protein levels in gliomas and peritumor tissues (15 cases) of The Second Hospital of Shandong University." (PMID 36527013, 2022). "CCNB1 and CDC2 play important roles in the proliferation of Glioma cells, the expression of PTTG1 is correlated with poor prognosis in Glioma patients, and aberrant splicing of CDKN3 increases proliferation and migration in Glioma cells." (PMID 21698123, 2011). "Impressively, CDC20, KIF20A and PTTG1 were naturally and highly co‐expressed in GBM glioma cells." (PMID 40047299, 2025). "No expression of securin, the protein translated from PTTG1, was found in EVs from the glioma patients by Western blot analyses." (PMID 31410219, 2019).
hepatocellular carcinoma (25 papers, 2008 to 2025). A malignant tumor that arises from hepatocytes. "PTTG1 plays a crucial role in hepatocellular carcinoma development by promoting asparagine metabolism and activating the mechanistic target of rapamycin pathway, indicating the potential of PTTG1 as therapeutic and diagnostic targets." (PMID 38465336, 2024). "RAC2 has been identified as a prognostic biomarker in clear-cell renal carcinoma, while PTTG1 has shown potential as a prognostic indicator in hepatocellular carcinoma due to its role in promoting β-catenin stabilization." (PMID 40072059, 2025). "It has also been shown to play the role of an inflammation-related oncogene in hepatocellular carcinoma Additionally, PTTG1 was found to induce epithelial–mesenchymal transition in colon carcinoma." (PMID 32824814, 2020). "Adenovirus vector assisted delivery of siRNA targeting PTTG-1 would be more efficient in down-regulation of PTTG-1 expression for hepatocellular carcinoma management." (PMID 29861465, 2018). "Overexpression of PTTG1 and its relationship with poor prognosis were observed in hepatocellular carcinoma and adrenocortical cancer." (PMID 28977903, 2017). "As in numerous neoplasms, such as pancreatic cancer, prostate cancer, lung adenocarcinoma, and hepatocellular carcinoma, PTTG1 overexpression is connected with tumorigenesis progression and poor prognosis; it constitutes a potential prognostic biomarker as well as a novel target for cancer therapy." (PMID 40072059, 2025). "In summary, we found that HSG (PTTG1, ANLN, KIF2C, TPX2) was significantly upregulated in hepatocellular carcinoma and that the constructed prognostic risk model can reliably predict the prognosis of hepatocellular carcinoma patients." (PMID 38887516, 2024). "However, PTTG1 at the metabolic level has only been reported in hepatocellular carcinoma, and its specific mechanism in lung adenocarcinoma needs to be further investigated." (PMID 39144144, 2024). "In summary, analysis of hepatocellular carcinoma revealed that HSS_high Hepatocytes exhibited stronger proliferative capacity and differentiation potential, regulated by multiple transcription factors to upregulate PTTG1 expression." (PMID 38887516, 2024). "The mechanisms of PTTG3P functions are not yet well understood, but it has been demonstrated that PTTG3P promotes both proliferation and invasion throght upregulation of PTTG1 and is an indicator of bad prognosis in cervical cancer and hepatocellular carcinoma." (PMID 32824814, 2020). "Therefore, it is important to elucidate the mechanism of PTTG1 involvement in the process of hepatocellular carcinoma development." (PMID 31385458, 2019). "PTTG1 was found to be clearly upregulated in hepatocellular carcinoma." (PMID 31385458, 2019). "Another study by our group revealed a different mechanism of PTTG1 suppression by T3/TRs, showing that T3 stimulation in TR-expressing hepatoma cells inhibited expression of specificity protein 1 (Sp1), thereby suppressing PTTG1, a direct transcriptional target of Sp1." (PMID 23878812, 2013). "It is essential to undertake research to identify specific downstream targets of the Wnt/β-catenin pathway activated by PTTG1 in hepatocellular carcinoma (HCC) to elucidate their contributions to tumor progression and poor prognosis." (PMID 40072059, 2025). "To explore the effects of PTTG1 on HCC cells, we utilized lentiviral knockdown of PTTG1 in the human hepatocellular carcinoma cell line Huh7 and assessed its cellular proliferative capacity." (PMID 38887516, 2024). "Moreover, knockdown of Sp1 or PTTG1 inhibited proliferation of TR-expressing hepatoma cells." (PMID 23878812, 2013).
hepatocellular carcinoma (continued). "Through the PI3K/AKT signaling pathway, PTTG1 appears to be an integral component in the complex network of factors controlling EMT, ultimately contributing to the metastatic potential of hepatocellular carcinoma cells." (PMID 40072059, 2025). "Furthermore, focusing on the key gene PTTG1 in HSG, we investigated its functions in hepatocellular carcinoma cells and Treg." (PMID 38887516, 2024). "Our data suggest that pituitary tumor transforming gene 1 (PTTG1) plays a vital role in inflammation‐related hepatocellular carcinoma (HCC) via c‐myc induction and that PTTG1 may be a potential therapeutic target for HCC." (PMID 31385458, 2019). "That study demonstrated the reciprocal expression of KLF6 and PTTG1 both in hepatocellular carcinoma (HCC) patient samples and in the HepG2 cell line, suggesting that the loss of KLF6 and the subsequent up-regulation of PTTG1 could contribute to tumorigenesis in HCC." (PMID 23977008, 2013).